ALB (albumin)
Diseases named in the same sentence as ALB in open-access papers (continued):
Sharing a sentence is not in itself a finding about the gene and the disease.
peritonitis (continued). "Decreased albumin and prealbumin concentrations associated with peritonitis in peritoneal dialysis patients have been mentioned by several authors." (PMID 33238904, 2020). "Of note, low albumin is described as a risk factor to the occurrence of peritonitis and mortality from infectious causes in PD cohorts." (PMID 31978190, 2020). "Low serum albumin was significantly associated with an increased incidence of peritonitis in our population." (PMID 31996157, 2020). "This study also showed that a lower serum albumin level was a significant risk factor for peritonitis, as previously reported." (PMID 31697753, 2019). "On logistic regression analysis, serum albumin < 1.5 g/dL was found as the only risk factor for major infections (OR 2.6; 95% CI, 1.2-6; p = 0.01) as well as peritonitis (OR 29; 95% CI, 3-270; p = 0.003)." (PMID 31528983, 2019). "In the past, serum albumin has been shown to predict all-cause mortality, and peritonitis risk in PD patients; however, the data are significantly more limited than for HD patients and most of the time based on small research studies." (PMID 25885318, 2015). "Studies in the United States and Hong Kong found that every 1 g/dL decrease of serum albumin concentration increased the risk of peritonitis by 74% and 67% respectively." (PMID 25222609, 2014). "Age, educational level, and albumin were associated with risk for the first episode of peritonitis in univariate Cox analysis, and were entered in the multivariate Cox proportional hazard model." (PMID 25222609, 2014). "Low levels of serum albumin have been shown to be associated with the risk of peritonitis in several previous studies." (PMID 23844107, 2013). "In three studies, albumin levels <3 g/dL or <2.9 g/dL, respectively, were associated with an approximately two-fold risk for peritonitis." (PMID 23320172, 2012). "Three studies showed an association between low albumin levels and a higher risk for peritonitis (HR 1.67; 1.08–2.60 per 10 g/L decrease, HR 0.73; 0.59–0.91 per 1 g/dL increase, and OR 1.2 (P = 0.05) per 1 mg/L, resp)." (PMID 23320172, 2012). "A sufficient amount of albumin is likely to improve intravascular volume and bind inflammatory cytokine, all of which are risk factors for the incidence of PD related peritonitis, resulting in technique failure of PD and increased hophitalization rate and mortality." (PMID 38698782, 2024). "At the same time, low albumin is considered a risk factor for peritonitis in PD patients." (PMID 36762995, 2023). "Our results also showed that a low level of serum albumin was a risk factor for the occurrence of technique failure of PD, which might be related to the increase in the incidence of peritonitis." (PMID 34233593, 2021). "Renal disease classified as “other or unknown” (HR 1.65; 95% CI 1.08–2.53) and serum albumin <3500 mg/dl (HR 1.49; 95% CI 1.04–2.15) were also associated with an increased risk of peritonitis." (PMID 23844107, 2013). "Furthermore, albumin levels <3500 mg/dl were also associated with an increased risk of peritonitis (HR 1.49; 95% CI 1.04–2.15)." (PMID 23844107, 2013). "On univariate analysis, six variables [including PD duration, serum albumin, antibiotics prior to admission, peritoneal dialysate white cell count on day 5 (/μl) ≥ 100/μl, 24-h urine volume ≥ 500 ml, and type of causative organisms] were significantly associated with peritonitis cure (P < 0.05)." (PMID 35559352, 2022). "In the multivariate Cox proportional hazards model, low levels of serum albumin (HR = 0.932, 95% CI 0.896–0.969, p = 0.004) and high peritoneal transport type (high and high-average) (HR = 1.872, 95% CI 1.349–2.599, p = 0.006) were independent risk factors for the first episode of peritonitis." (PMID 34233593, 2021). "The albumin/ascitic protein ratio < 2.5 was assigned 2 points, reflecting its strong clinical relevance in the pathophysiology of spontaneous peritonitis." (PMID 41353185, 2025).
peritonitis (continued). "PD patients with an initial serum albumin level less than 29 g/L had a peritonitis rate of 1.5 episodes/dialysis-year compared with 0.6 episodes/dialysis-year for patients with ≥29 g/dL (p < 0.001)." (PMID 39944488, 2025). "For morbidity, independent predictors were the extent of peritonitis, the open surgery, postoperative albumin levels, and p-SOFA scores." (PMID 39709362, 2024). "Lowest values for serum albumin concentration, and highest values for serum urea and creatinine concentration were detected in the group of calves with a diagnosis of peritonitis." (PMID 36661389, 2023). "Patients with HaP had lower mean serum albumin levels at the time of diagnosis of peritonitis compared to patients with CaP (22.95 g/L vs. 25.68 g/L, p = 0.002)." (PMID 36913080, 2023). "Our study revealed that patients in the HaP group had lower mean serum albumin levels at the time of peritonitis diagnosis compared to the CaP group (22.95 g/L vs. 25.76 g/L, respectively)." (PMID 36913080, 2023). "The number of dWBC on day 3 in the LDD group was significantly higher than that in the SDD group (p = .003), whereas the serum albumin level during peritonitis was significantly lower in the LDD group than that in the SDD group (p = .026)." (PMID 36786676, 2023). "Albumin levels, peritonitis, and RRF at the beginning of PD and at 3-month periods during PD were recorded." (PMID 36762995, 2023). "A significant association was found between low serum ALB level at the time of initiation of continuous ambulatory peritoneal dialysis (CAPD) and the development of peritonitis." (PMID 37790129, 2023). "We found that a high serum albumin level was good for the cure of PDAP, and it was assumed that treatment strategies to improve albumin levels should be advocated to improve the treatment outcome of peritonitis." (PMID 35559352, 2022). "It was observed in this dataset that a higher level of serum albumin predicted a higher probability of peritonitis cure." (PMID 35559352, 2022). "The univariate analysis showed the usage rate of antibiotics in the month before the onset of peritonitis was higher (45.45 vs. 15.93%) and the mean serum albumin was lower (31.4 vs. 34.4 g/L) in the FP group when compared with BP group (P < 0.05)." (PMID 34277521, 2021). "Previous study in Turkey reported that among 86 cases of peritonitis, 9 were FP (10.5%), and these had significantly lower serum albumin than the BP cases." (PMID 34277521, 2021). "Bei der „Large-volume“-Parazentese, der spontanen bakteriellen Peritonitis, aber auch beim hepatorenalen Syndrom ist der Einsatz von Albumin aufgrund eines klinischen Benefits in randomisierten kontrollierten Studien klar empfohlen und etabliert." (PMID 34618163, 2021). "The results showed that age, decreased serum albumin level, and increased serum CRP levels remained independent risk factors for peritonitis (p < 0.05) in the multivariate analysis." (PMID 32781861, 2020). "The peritonitis group had lower serum albumin, lower blood leukocyte, lower hemoglobin and lower platelet count as compared to the non-peritonitis group." (PMID 32787649, 2020). "We also found that OH and serum prealbumin were the independent predictors of peritonitis compared to other factors, such as glucose, serum albumin, and hs-CRP (AUC of prealbumin was 0.838 and that of OH was 0.851, p < 0.001)." (PMID 33238904, 2020). "In the univariate models, low serum albumin level and PPI use were significantly associated with overall peritonitis." (PMID 31697753, 2019). "Multivariate adjustment for clinically relevant factors attenuated the association between low serum albumin (per 1 g/dl adjusted HR = 0.59, 95% CI): 0.39–0.90; P = 0.014), PPI use (HR, 1.73; 95% CI, 1.12–2.68; P = 0.013), and peritonitis." (PMID 31697753, 2019).
peritonitis (continued). "A smaller Chinese study (n=258) found that BMI, albumin, albumin/globulin ratio, CRP, and fast peritoneal solute transfer rate were independent risk factors for peritonitis in patients undergoing continuous ambulatory peritoneal dialysis using multivariate logistic regression." (PMID 41001563, 2025). "The outcomes reported showed intense diversity among the studies, ranging fromclinical indicators (hospitalization, peritonitis, emergencies, mortality),laboratory parameters (hemoglobin, phosphorus, albumin, calcium, cholesterol),blood pressure levels, to variables related to user satisfaction." (PMID 38055586, 2023). "Lower serum albumin was associated with higher odds of refractory peritonitis but showed no statistical difference in the odds of PD-catheter removal." (PMID 36913080, 2023). "In our study, univariate analysis revealed that PD duration, serum albumin (before peritonitis), phosphate (before peritonitis), serum albumin (at onset), dWBC on day 0, dWBC on day 3, blood leukocyte count were strongly associated with treatment failure of peritonitis." (PMID 36786676, 2023). "However, when compared with the first year and mean albumin levels, there was a significant increase in peritonitis rates in those with low albumin levels." (PMID 36762995, 2023). "According to the literature, the most common risk factors for anastomotic fistula are pulmonary disease, previous albumin < 3.0 mg/dL, preoperative peritonitis, anastomotic strain, poor local blood supply to the anastomosis or infection, and presence of cancer and drainage placement." (PMID 36482551, 2022). "After adjusting for age, sex and serum albumin levels, we found that the combinations of low PTH levels with either high Ca levels or low/normal P levels were significant risk factors of developing peritonitis." (PMID 33441921, 2021). "In the multivariate model adjusted for albumin, prior Tx was not a risk factor for peritonitis [HR 1.41 (95% CI 0.78–2.56); p = 0.25]." (PMID 31978190, 2020). "Lower albumin level would thus contribute to the development of peritonitis." (PMID 31830041, 2019). "In a multivariate analysis using Backwards Wald Method, only albumin levels but not calcium levels were significantly associated with peritonitis and all-cause mortality." (PMID 23844107, 2013). "After adjusting for covariant factors, including DM, age at the time of the study, BMI, and the mean serum albumin level, the HR for peritonitis development was significantly higher in group 2 (HR = 1) than in group 4 (HR = 0.401, 95% CI 0.209 − 0.769) and the other 2 groups." (PMID 24007461, 2013). "However, patients with peritonitis had a higher high-sensitivity C-reactive protein (hsCRP) and lower levels of serum albumin (Alb) as compared with the control patients (P<0.05)." (PMID 23359306, 2013). "This may suggest that although baseline albumin is associated with peritonitis risk, it is not as determinative as the mean and first-year mean albumin levels." (PMID 36762995, 2023). "For example, we could not assess the effect of serum albumin, a well-known contributing factor for the development of PD-associated peritonitis." (PMID 31830041, 2019). "Our PD patients had a lower vintage and their symptom burden may reflect the initial difficulties in adjusting to life on dialysis, lower haemoglobin and albumin concentrations, as well as the occurrence of complications such as peritonitis and catheter exit site infection." (PMID 28056851, 2017). "Peritoneal analysis indicated a serum ascites albumin gradient (SAAG) of less than 1.1, suggesting peritonitis with neutrophil predominance." (PMID 40821222, 2025). "Red blood cells, pre-albumin, albumin, ultrasensitive C-reactive protein (CRP), white blood cells (WBC), lymphocytes, neutrophils, globulins, and the incidence of peritonitis were measured." (PMID 39612406, 2024). "Urea, body weight, K, albumin, DBP and SBP are important indicators for PD-related peritonitis deaths." (PMID 38106617, 2023).
peritonitis (continued). "To evaluate the peritonitis-induced barrier destruction, we determined protein- and FITC-albumin extravasation into the peritoneal cavity." (PMID 32210974, 2020). "Compared with the peritonitis-free patients, the patients with the first episode of peritonitis had advanced age, higher levels of CCI score, ALP, HsCRP (P<0.05) and lower levels of serum albumin (P<0.05)." (PMID 25222609, 2014). "However, in three studies the association between low levels of albumin and the risk for peritonitis could not be confirmed." (PMID 23320172, 2012). "Paracentesis demonstrated yellowish, predominantly lymphocytic fluid with a low serum ascites albumin gradient and low total protein (1.71 g/dL), while peritoneal biopsy indicated mild chronic nonspecific peritonitis." (PMID 41776681, 2026). "Additionally, the type of surgery (open versus laparoscopic), the severity of peritonitis, p-SOFA, and postoperative albumin levels were found to independently predict complications." (PMID 39709362, 2024). "Furthermore, it was determined that undergoing open surgery compared to laparoscopic surgery, the extent of peritonitis, p-SOFA, and postoperative albumin levels serve as independent predictors for complications." (PMID 39709362, 2024). "However, we have not encountered a comprehensive study on which of the mean albumin values, at the beginning of peritoneal dialysis, in the first year, and during the peritoneal dialysis period, provide more predictive predictions regarding mortality, peritonitis risk, and RRF reduction." (PMID 36762995, 2023). "In contrast to our study, one article considered that the serum albumin level did not influence the non-resolution of peritonitis." (PMID 35559352, 2022). "Patients in the peritonitis group had a lower level of serum albumin when compared with the non-peritonitis group." (PMID 34233593, 2021). "The average serum albumin and prealbumin levels in the peritonitis group were significantly lower than those in the nonperitonitis group (p < 0.001)." (PMID 33238904, 2020). "Because variations in serum albumin levels are small, measurement of changes in CRP levels may provide greater insight into the dynamics of nutritional status and clinically relevant insults such as peritonitis." (PMID 24007461, 2013).
Anorexia (82 papers, 2005 to 2026). Lack of desire to eat (loss of appetite). "On the other hand, albumin level correlates inversely with leptin level, suggesting increased leptin secretion in a hypoalbuminemic state, causing anorexia." (PMID 40045433, 2025). "The eight variables that were significantly associated with PTB in univariable analyses and included in the multicomponent diagnostic model were the respiratory rate, oxygen saturation, dyspnea, anorexia, general weakness, weight loss, albumin, and sodium." (PMID 37957334, 2023). "Inflammation caused anorexia, reduced the effective use of protein and energy intake in the diet, and enhanced the catabolism of key albumin." (PMID 35369313, 2022). "Low serum albumin levels resulting from inflammation-induced capillary leakage or disease related anorexia during acute illness are associated with poor outcomes." (PMID 36324111, 2022). "64‐year‐old cachectic female with a remote history of colon cancer, poor performance status (ECOG = 2), uncontrolled HTN, and COPD on 2 L supplemental O2 presented with an unexpected weight loss of 20 lbs over the last 6 weeks (BMI = 17; serum albumin 2.2 g/dL), with anorexia and fatigue." (PMID 40693544, 2025). "Albumin synthesis may decrease due to anorexia caused by chemotherapy and inflammation by radiotherapy, which is consequently associated with short survival." (PMID 37043179, 2023). "Decreased ALB in CKD may be associated with reduced production from anorexia or increased urinary loss in protein losing nephropathy." (PMID 36855344, 2023). "Additionally, the irregular dietary intake of vitamin K due to anorexia, nausea or vomiting, low body weight, and low albumin can cause instability for INR." (PMID 36233581, 2022). "This creates a detrimental cycle where inflammation leads to anorexia, hampers protein and energy utilization, and accelerates albumin degradation." (PMID 40585729, 2025). "The present data show a tendency of lower serum albumin levels in the anorexia group compared to the non-anorexia group (3.4 g/dL vs. 3.9 g/dL, p = 0.06)." (PMID 40045433, 2025). "Thus, patients with low albumin levels may be more susceptible to develop anorexia and nausea." (PMID 40045433, 2025). "In dogs with resting hypocortisolemia, the combination of anorexia and lethargy, along with low sodium and albumin concentrations, should raise the suspicion of hypoadrenocorticism." (PMID 39764376, 2024). "Multivariate analysis developed a robust model in which lethargy (OR 5.25), anorexia (OR 3.69), albumin (OR 0.32), and sodium (OR 0.84) concentrations allowed the prediction of HA." (PMID 39764376, 2024). "In conclusion, this study observed that multiple variables are associated with an increased likelihood of HA diagnosis, particularly lethargy, anorexia, and low sodium and albumin concentrations." (PMID 39764376, 2024). "Previous study has suggested that low serum albumin levels resulting from inflammation-induced capillary leakage or disease-related anorexia during acute illness." (PMID 38088961, 2023). "Inflammation induces anorexia, reduces the effective use of dietary protein and energy intake, and augments catabolism of the key somatic protein, albumin." (PMID 33260603, 2020). "The reduction in total protein, albumin, and globulin levels might be attributed to their decreased production due to the hepatic cell damage caused by the direct and indirect effects of Anaplasma species and the loss of appetite (anorexia) that is associated with the disease." (PMID 33061222, 2020). "A vicious cascade of events ensues in which inflammation induces anorexia and reduces the effective use of dietary protein as well as augmenting the catabolism of the key somatic protein, albumin." (PMID 28056937, 2017). "The cascade of events arising from inflammation induces anorexia and reduces the effective use of dietary protein and energy intake, thus increasing the catabolism of albumin." (PMID 28866982, 2017).